MMP7 (matrix metallopeptidase 7)
Diseases named in the same sentence as MMP7 in open-access papers (continued):
Sharing a sentence is not in itself a finding about the gene and the disease.
cancer (continued). "The difference between normal cells and cancer cells was considered to be related to the difference in the expression level of MMP7." (PMID 35186883, 2022). "Meta-analyses were conducted for assessing the relations among variants in MMP-2, MMP-7, and MMP-9 and cancer risk." (PMID 35574300, 2022). "In the two gene clusters, some genes associated with tumorigenesis and cancer progression, such as AGR2, MMP7, LXN, PIGR, and CRABP2, were identified." (PMID 36712886, 2022). "MMP-7 expression, which appeared as red staining, was distributed heterogeneously in the cytoplasm of cancer cells." (PMID 35496040, 2022). "Considering that, this study has the largest scale and is an integrative study that evaluates the relations of MMP-2, MMP-7, and MMP-9 variants with cancer susceptibility." (PMID 35574300, 2022). "A large number of studies have demonstrated that MMP-7 acts in the development and migration of cancer." (PMID 36776395, 2022). "PubMed, Web of Science, and Medline were systemically searched, and data were extracted from all eligible studies so as to investigate the susceptibility of MMP-2, MMP-7, and MMP-9 to different types of cancers." (PMID 35574300, 2022). "Studies have shown that MMP-7 can protect cancer cells from chemotherapeutic drugs by modulating Fas expression and activation as well as the cleavage of both Fas and FasL, thus blocking the Fas-dependent apoptotic effect of the drug." (PMID 35586209, 2022). "In this context, here, the meta-analysis was conducted for assessing the relations of variants in MMP-2, MMP-7, and MMP-9 with the risk of various cancers." (PMID 35574300, 2022). "Previously published studies revealed the role of MMP-7 in chemotherapy (including cisplatin) resistance in various cancers." (PMID 35327500, 2022). "Due to the intricacy of MMP7 in tumorigenesis, it is requisite to conduct a pan-cancer analysis on the correlation between MMP7 and various human cancers based upon big clinical data." (PMID 35785154, 2022). "These peptides encapsulated a large amount of DOX to form fibrils, undergone morphological changes triggered by MMP7 in certain cancer cells, released drug molecules, and accumulated in the cancerous area to provide targeted delivery." (PMID 35186883, 2022). "More and more evidence has shown that MMP7 plays a critical role in the genesis and development of tumors by reducing cell adhesion, inhibiting cancer cell apoptosis, and inducing vasculogenesis." (PMID 35785154, 2022). "Expression of γ2pf, an additional invasive marker commonly seen in cancer cells, was increased in MMP7-positive cells in the intermediate and chronic phases." (PMID 34728556, 2022). "MMP gene variants (e.g., MMP-2, MMP-7, and MMP-9) can affect the biological functions of these enzymes and lead to the occurrence and progression of cancer, which has become a hot topic in recent years, but the corresponding results are still controversial." (PMID 35574300, 2022). "As the GPLGLA motif is the substrate for MMP7, this peptide cleavage occurred selectively at cancer cells, allowing targeted drug delivery." (PMID 36354614, 2022). "In an approach taking advantage of metalloproteinase 7 (MMP7) overexpression in cancer cells, Cao used this enzyme to promote the gel-to-sol transition of Nap–FFGPLGLARKRK peptide." (PMID 36354614, 2022). "Although numerous studies have reported associations between MMP-2, MMP-7, and MMP-9 variants and cancer risk, these results are highly controversial." (PMID 35574300, 2022). "Activation of the PKC pathway led to an increase in MMP-7 and 10 in cancer cells, indicating their involvement in cell proliferation and migration in OC." (PMID 35145899, 2021). "The remaining factors, including β-catenin, MMP7, E-cadherin, and HIF1-α, are closely associated with the formation of the cancer microenvironment." (PMID 34490089, 2021).
cancer (continued). "High MMP-7 level is an independent predictor of docetaxel resistance and poor cancer survival in patients with castration-resistant prostate cancer (CRPC)." (PMID 33918254, 2021). "MMP-7 is produced by the stromal cells surrounding cancer cells and by the cancer cells themselves, as in invasive tumor cells in which it is often overexpressed." (PMID 34944575, 2021). "The results presented above regard different types of cancer than BC, but reveal a similar trend, i.e., elevated levels of MMP-7 in cancer patients, high values of SE and SP and higher values of AUC compared to AUC = 0.5." (PMID 33916127, 2021). "An enzyme immunoassay test revealed higher MMP-7 levels in cancer tissue in comparison to healthy tissue." (PMID 33916127, 2021). "Despite these characteristics of MMP-7 in cancer, clinical use of MMP-7 inhibitors has been disappointing due to its poor therapeutic effect and side effects." (PMID 34502094, 2021). "Msln-mediated secretion of MMP-7 in MUC16-expressing cancer cells occurs via a p38 MAPK-dependent pathway." (PMID 34966784, 2021). "Depletion of MMP-7 or inhibition of p38 activity abolishes MSLN-mediated cancer cell motility and invasion." (PMID 34966784, 2021). "Matrilysin, also known as MMP7, promotes cancer invasion in several processes including proteolytic cleavage of ECM proteins." (PMID 34834411, 2021). "Overexpression of MMP-7 is observed in ~80% of CRC, and serum levels of MMP-7 are associated with cancer progression and decreased survival in advanced CRC." (PMID 34502094, 2021). "Zn level was not considered in previous studies investigating association of MMP-1, MMP-2, MMP-7, MMP-13 and MT2A polymorphism with cancer risk." (PMID 32765800, 2020). "Because so many studies have confirmed the carcinogenesis of MMP7, the diagnosis, prognosis, treatment and prevention of malignant tumour patients targeting MMP7 were explored to improve the unfavorably poor clinical outcome." (PMID 31937294, 2020). "Ube2S overexpression, by transfecting cDNA into cancer cells, significantly upregulated the expression of β-catenin, cyclin D1, and MMP7 proteins, novel members of the canonical Wnt signaling pathway (p < 0.05)." (PMID 32038111, 2020). "It has been demonstrated that the overexpression of MMP7 enhances cancer invasion and metastasis[37 ▶-39 ▶]." (PMID 32429632, 2020). "High level of MMP7 expression accelerates cancer invasion and angiogenesis by cleavage of ECM and connective tissues." (PMID 35047986, 2020). "Further studies are required for better understanding of the mechanism underlying cancer progression that involves the link between MMP24 and MMP7." (PMID 32093160, 2020). "IL7R and IL7 are highly expressed in PCa and are associated cancer cell invasion and migration probably by activating the AKT/NF-κB pathway and upregulating MMP-3 and MMP-7 expression." (PMID 32704070, 2020). "During cancer progression, MMP7 degrades cell surface proteins, promotes adhesion of cancer cells, and consequently promotes tumor metastasis." (PMID 35047986, 2020). "The present review discusses the recent findings related to MMPs, particularly MMP-2 and MMP-7, and their involvement in various cancers." (PMID 32751899, 2020). "Perlecan cleavage by matrix metalloproteinase-7 (MMP-7) facilitates cancer cell-ECM adhesion, dispersion and eventually leads to bone metastasis via induction of FAK-dependent invasion." (PMID 33330449, 2020). "Of these, HMGA2 was reported participating in the proliferation of many cancer types, and MMP7 was found affecting the apoptotic process mediated by FAS/FASL system as well as N-cadherin." (PMID 32874135, 2020). "According to previous studies, degrading the components of basement membrane and ECM by MMP7 is a basic step of malignant carcinoma cell migration." (PMID 31937294, 2020). "Our results suggest that syndecan-2-mediated regulation of cancer activity depends on its interaction with and activation of MMP-7." (PMID 31337828, 2019).
cancer (continued). "MMP-7 was found to function as a prometastatic factor by promoting the migratory and invasive ability of cancer cells, and overexpression of MMP-7 was found in HCC specimens and cells, favoring EMT." (PMID 31886121, 2019). "MMP-7 is considered to play an important role in invasion and metastasis in a variety of cancer cells, and it is reported to be elevated in SAS59,60." (PMID 31350432, 2019). "Emodin, an active anthraquinone present in A. vera, inhibits cancer growth by suppressing the expression of MMP7, MMP9, VEGF, EMT, N-cadherin, β-catenin, and Snail." (PMID 30871059, 2019). "Inhibition of GP73 blocks the trafficking of intracellular MMP-7 and leads to repression of cancer cell invasion." (PMID 31591387, 2019). "This reduced enzymatic activity was associated with reduced extracellular domain shedding of syndecan-2 and E-cadherin, which are well-known substrates for MMP-7 in cancer cells." (PMID 31337828, 2019). "Of them, matrix metalloproteinase-7 (MMP-7) has been well studied for its roles in cancer progression." (PMID 31337828, 2019). "The DCGs, including GART, TGFB1, ITGA2, SLC16A5, SOX9, and MMP7, were investigated across 12 cancer types." (PMID 29843204, 2019). "Duodenal polyps in this study also exhibited upregulation of CD44, a cancer stem cell marker associated with PGE2 signaling, and MMP7, which encodes a matrix metalloproteinase and is a Wnt/Beta-catenin signaling target." (PMID 31211760, 2019). "The metalloproteinases MMP7 and MMP9 are overexpressed in NSCLC and other types of cancers and are strongly associated with poor prognosis." (PMID 29631554, 2018). "Both MMP7 and CCN2 have been associated with poor prognosis in different types of cancer and with fibrotic or inflammatory diseases." (PMID 29941541, 2018). "Differential expression of MMP-7 was highly significant in which MMP7 expression was barely detectable by qPCR in benign ovarian tissues (Cq = ~30) but highly expressed in cancer (Cq = 25) representing striking increases of 370-fold." (PMID 29581841, 2018). "We found that cells with ADH1B expression secrete MMP-7, CD-26, and cathepsins, which promote cancer progression by their action as proteases." (PMID 29861857, 2018). "MAG inhibits cancer metastasis by reducing the expression of matrix metalloproteinase-7, -9 (MMP-7, -9) and urokinase plasminogen activator (uPA)." (PMID 30103472, 2018). "Because myofibroblasts play important roles in defining the cancer microenvironment and cancer progression we examined the biology of MMP‐7 in myofibroblasts in more detail." (PMID 29845775, 2018). "MMP7 is increased in many malignant cancer types and is secreted specifically from epithelial cells." (PMID 29250491, 2017). "In this regard, Kesh and colleagues showed increased expression of MMP-7 in cancer patients carrying the GG genotype." (PMID 29317790, 2017). "Determination of MMP-7 levels in NSCLC, benign and healthy controls displayed a statistical significant increase in cancer patients, though a moderate discriminatory capacity was found for MMP-7 (AUC: 0.604)." (PMID 29207990, 2017). "It should be emphasised that the areas under the ROC curve in various stages of cancer for MMP-7 in combination with HE4 or CA125 were as large as those for the combination of CA125 and HE4." (PMID 28662671, 2017). "Although MMPs are typically expressed by stromal cells, MMP7 was chosen due to its established expression exclusively by carcinoma cells." (PMID 28276469, 2017). "MMP-7 expression also demonstrated the highest [cancer]/[normal] mean value deviation from 1.0 with 2.54 and 2.38 for G4/NG and TS/NS, respectively." (PMID 26862737, 2016). "Given that MMP7 is a potential “druggable” target on cancers in clinics, mechanisms on ARF-MMP7 inhibition would produce valuable information on the development of effective therapeutic treatments." (PMID 27356744, 2016).
cancer (continued). "On the other hand, dysregulation of PTEN/PI3K pathways contributes to cancer progression through activation of downstream oncogenic pathways including MMP7, yet the mechanism on the aberrant elevation of MMP7 is puzzling." (PMID 27356744, 2016). "In aggressive PCa cancers, MMP-7 is upregulated in relation to its natural inhibitor, tissue inhibitor of MMP 1 (TIMP-1), and PCa overexpressing MMP-7 displays increased invasiveness in a murine model of metastasis." (PMID 26862737, 2016). "Each cancer and normal tissue type was quantified for perlecan and MMP-7 stain concentration, normalized, and the correlation coefficients analyzed." (PMID 26862737, 2016). "MMP-7 is an established instigator of aggressive behavior in a number of cancer types including NSCLC." (PMID 26840018, 2016). "We demonstrated that ARF tumor suppressor stimulates the nuclear shuttling of MMP7 in PCa cells during cancer evolution." (PMID 27356744, 2016). "The effect can be regulated by proteolytic digestion of the inhibitory peptide by the matrix metalloproteinase MMP-7, an enzyme upregulated in many malignant tumors." (PMID 26892926, 2016). "Some target genes are involved in oncogenesis, such as c-MYC and cyclin D1 regulating cancer proliferation, MMP-7 regulating cancer invasion." (PMID 25658088, 2015). "Our study demonstrated that mechanical signal transduction promoted cancer cell viability by increasing MMP-7 expression." (PMID 26344692, 2015). "The aims of this study were to compare tissue levels of TIMP-1, COX-2 and MMP-7 in cancer, polyps and control groups to reveal their impact in carcinogenesis and metastasis." (PMID 29201696, 2015). "A potential mechanism underlying SGC-7901 tumorigenicity is the activation of the Wnt/β-catenin signaling pathway, which activates uPA and MMP-7 expression and contributes to the enhanced invasion of hypoxic cancer cells." (PMID 25997455, 2015). "These were consistent with previous reports, as MMP7 and other members in the matrix metallopeptidase family were reported to play important roles in extracellular matrix turnover, cancer cell migration, cell growth, inflammation, and angiogenesis." (PMID 26517713, 2015). "We demonstrated that a stiff substrate increased the expression of MMP-7, including degradation of the basement membrane, that would likely aid in the development of improved cancer therapy." (PMID 26344692, 2015). "We inferred from these results that MMP-7 promotes poor cancer prognoses by accelerating cancer cell proliferation." (PMID 26344692, 2015). "We then examined the influence of EGF on MMP9 transcription as well as on the transcription of additional MMPs (MMP-1, MMP-2, MMP-3, MMP-7, MMP-10, MMP-13, MMP14, MMP15) and of CD44, a cell adhesion glycoprotein implicated in EMT and cancer metastasis." (PMID 26084289, 2015). "Some previous studies have revealed that EGFR and integrin-β1 regulate MMP-7 expression; however, to the best of our knowledge, it has not been previously reported that integrin-α2, MRLC and YAP regulate MMP-7 expression in cancers." (PMID 26344692, 2015). "It has been suggested that a positive relationship exists between MMP-7 expression and the invasive potential of cancer cells." (PMID 26699938, 2015). "MMP-7 is often overexpressed in a variety of malignant tumors including colon cancer, gastric carcinoma, and squamous cell carcinoma of tongue and oral cavity." (PMID 26699938, 2015). "The cut-off value for MMP-7 was 33.62 and the probability of developing cancer was 80 times higher in values above 33.62 compared to the values below 33.62 (10.1-635.7)." (PMID 29201696, 2015). "Elevated levels of MMP7 have been reported in many cancer types (gastric, esophageal, colorectal, pancreatic, prostate, head and neck, lung, hepatocellular and breast), as well as in cancer premalignant lesions (pancreas, stomach, colon, breast and prostate)." (PMID 25919283, 2014).
cancer (continued). "Western blotting study shows that downregulation of Btbd7 in NCI-H1299 cells significantly upregulated E-cadherin expression and downregulated snail 2 (slug), MMP2 and MMP7 expression in cancer cells." (PMID 25253020, 2014). "Serum levels of MMP-7 are associated with decreased survival in advanced CRC and correlate with cancer progression." (PMID 24518611, 2014). "The TCF/LEF downstream molecules c-myc, cyclin D1 and MMP7 were also increased significantly in cancer cells." (PMID 23737966, 2013). "Consistently, DSG3 over-expression and plakoglobin translocation was found in the cancer tissues, in concurrence with up-regulations of c-myc, cyclin D1 and MMP-7." (PMID 23737966, 2013). "In cancer epithelial cells, β-catenin is translocated into the nucleus, which activates oncogenes including MMP-7." (PMID 24261884, 2013). "At the molecular level, MMP2, MMP7 and MMP9 are associated with cell migration process, influencing cancer development and progression." (PMID 24098538, 2013). "Among the variety of MMPs, MMP2, MMP7, and MMP9 were more commonly associated with cancer metastasis as they have the ability to degrade collagen type IV which is the major component of basement membrane." (PMID 24138815, 2013). "MMP-7 is produced mainly by glandular epithelial cells and macrophages in diseased tissues and is overexpressed by cancer cells in human tumors." (PMID 24336111, 2013). "MMP7 is a target of beta-catenin transactivation in certain tumors and evidence show the involvement of MMP7 activation in human cancer metastases." (PMID 24143235, 2013). "In our comprehensive meta-analysis, MMP1 (−1607)1G/2G, MMP7 (−181) A/G and MMP9 (−1562) C/T were shown to increase the risk of cancer metastasis, whereas MMP3 (−1171) 5A/6A was protective in metastasis." (PMID 22348060, 2012). "On the other hand, a strong MMP-2, MMP-9 or MMP-7 signal in cancer cells has been found to predict better survival." (PMID 22200690, 2012). "It has been found that MMP-7 is overexpressed in the invasive cancers of digestive organs, such as oesophageal, gastric, pancreatic, colorectal, liver and other organs." (PMID 20939893, 2010). "The most impressive enhancement (>20-fold) in carcinomas compared to normal tissue, however, was noted for MMP-7." (PMID 16538217, 2006). "Although the mediators involved in MSLN signal transduction may vary in a cancer-specific manner, they appear to converge on a common downstream target: the MMP7 gene." (PMID 41335396, 2025). "MMP-7 inhibits apoptosis in cancer cells, decreases cell adhesion, and induces angiogenesis." (PMID 41462922, 2025). "Notably, treatment with PTX and 6-Glucan resulted in the downregulation of BCL2, Survivin, MMP7, and TGF-β in sorted MDA-MB-231 CSC mammospheres, indicating a decrease in gene expression levels associated with these cancer-related processes." (PMID 39955575, 2025). "This higher MMP7 expression was found to enhance the proliferation and invasion of cancer cells." (PMID 39187937, 2024). "In our study, we observed co‐localisation of APOE+ TAMs and MMP7+ cancer cells in the TME." (PMID 39187937, 2024). "APOE+ TAMs may secrete factors that induce MMP7 expression in nearby cancer cells, enhancing their invasive capabilities." (PMID 39187937, 2024). "Notably, the downregulation of HSP47 led to a significant decrease in matrix metallopeptidase-7 (MMP-7) expression, a gene closely associated with cancer cell migration and invasion." (PMID 38907287, 2024). "However, MMP7 is one of the several MMPs that are inhibited by doxycycline, which is a commonly used treatment for various forms of cancer." (PMID 39057065, 2024). "Trigonelline also inhibited the gene expression of zinc-dependent matrix metalloproteinase-7 (MMP-7), an endopeptidase that degrades extracellular matrix, reduces cancer cell adhesion, and inhibits apoptosis, thereby suppressing tumor migration and progression." (PMID 37110693, 2023).